ERBB3 (erb-b2 receptor tyrosine kinase 3)
Diseases named in the same sentence as ERBB3 in open-access papers (continued):
Sharing a sentence is not in itself a finding about the gene and the disease.
ovarian carcinoma (continued). "An autocrine signal-transducing loop involving ErbB3 and its activating ligand HRG has been found to promote cell proliferation in human ovarian cancer cells and the effects of HRG/ErbB3 were abrogated by genetic or pharmacological ErbB3 inhibition." (PMID 31728045, 2019). "IGF-1R can interact with multiple RTKs that are overexpressed in ovarian cancer, such as EGFR, HER2, ErbB3 and c-Met3." (PMID 31728045, 2019). "Together, these data point to ErbB3 as potentially critical RTK in the treatment of IGF-1R positive tumors, such as ovarian cancer." (PMID 31728045, 2019). "Interestingly, the level of HER2 in ovarian cancer below which seribantumab provides benefit (~126,000 receptors/cell) closely matches the level predicted by computational modeling and preclinical experiments in which seribantumab potently inhibits ErbB3 phosphorylation." (PMID 28725482, 2017). "The neuregulin/ErbB3 signaling module is important for activation of the PI3K pathway, and promotes cell growth in a subset of ovarian cancer." (PMID 26095858, 2015). "More recently, an activated ERBB3/NRG1 autocrine loop has been demonstrated to support tumor cell proliferation in a subset of primary ovarian cancers and ovarian cancer cell lines." (PMID 21962244, 2011). "A humanised monoclonal antibody that binds to the extracellular domain of Her2 and blocks its heterodimerisation with ErbB3 and other EGFR family members, pertuzumab (2C4), has been explored in clinical trials in ovarian cancer." (PMID 21364581, 2011). "ERBB3 and ERBB4 have been shown to be upregulated in chemoresistant ovarian cancer and upregulation was observed in Indian ovarian cancer, which might serve as a potential therapeutic target." (PMID 37091785, 2023). "Furthermore, ERBB3/NRG1 signaling activates PI3K and SRC pathways, which promoted epithelial-to-mesenchymal transition and CTC formation of ovarian cancer cells." (PMID 29321816, 2017). "Notably, ERBB3 and ERBB4 are the predominantly expressed EGFR family members in ovarian cancer, where they showed marked expression in 76% and 98% of all cases in a recent study." (PMID 26745281, 2016). "More recently, signalling through the ErbB3 pathway has been reported to correlate with expression of its natural ligand, neuregulin-1 (NRG1) in both ovarian cancer cell lines and in primary human ovarian cancer cells." (PMID 21364581, 2011). "Notably, the OVCAR5 cell lines used in this study exhibit no ErbB3 signaling, and the TOV21G and lgrov-1 cells express low levels of ErbB3 protein, suggesting that the expression of erbB3 and Gab2 contribute to activation of the PI3K pathway in different subsets of ovarian cancer." (PMID 26095858, 2015). "Collectively, these results show that ErbB2 and ErbB3 control basal, constitutively active levels of pAkt and down regulation of ErbB2 and ErbB3 contributes to α-TEA-induced suppression of pAkt and induction of apoptosis in both A2780S and A2780/CP70R human ovarian cancer cells." (PMID 20224651, 2010). "Our analysis of correlation between RTK expression and chemotherapy sensitivity in multiple ovarian cancer cell lines suggested a correlation for IGF-1R and cMET expression, but not ErbB3." (PMID 31728045, 2019).
colorectal cancer (78 papers, 2005 to 2025). A primary or metastatic malignant neoplasm that affects the colon or rectum. "Even though ErbB3 homodimers possess little autophosphorylation activity, however, ErbB3 is often overexpressed in colorectal cancers when associated with ErbB1 and ErbB2." (PMID 35800225, 2022). "Loss of ErbB3 expression in poorly differentiated colorectal cancer cells increases sensitivity to gefitinib." (PMID 35872794, 2022). "Across all colorectal cancer data sets in cBioPortal (n = 4453), an average of 5% of all colorectal cancers harbor an ERBB3 mutation, with several of these being considered hotspot mutations." (PMID 36551663, 2022). "Several studies already reported an association between ERBB3 expression and patients’ outcome in different types of cancer, including lung adenocarcinoma, breast, gastric, and colorectal cancer." (PMID 33799723, 2021). "In recent studies, it was observed that anti-ErbB2 targeted therapy can cause compensatory overexpression of ErbB3 in breast and colorectal cancers." (PMID 30621788, 2019). "Elevated levels of ERBB3 expression have been associated with decreased patient survival in colorectal cancer." (PMID 26367378, 2015). "Here, we investigate whether ERBB3 is associated with intestinal stem cell markers in colorectal cancer and if cancer stem cells within tumours are marked by expression of ERBB3." (PMID 26367378, 2015). "For example, a 3-mm TA harbored one of the highest MB of 6.45, with pathogenic mutational defects in numerous colorectal cancer driver genes (e.g., APC, SOX9, TCF7L2, ASXL1, ERBB3, MAP2K1, and PTPRS)." (PMID 40757636, 2025). "Together, these findings suggest that specific metabolites produced by intestinal bacteria can activate critical targets such as NF-κB, PI3K/AKT, and ErbB2/ErbB3, thereby contributing to the development of colorectal cancer." (PMID 39948481, 2025). "All these kinases displayed mutations in more than 6% of CDX2-suppressed colorectal cancers in the TCGA cohort, and some receptor tyrosine kinases, including EGFR, ERBB3, ERBB4, RET, ROS1, and ALK, showed even higher mutation rates in these cancers." (PMID 39452477, 2024). "HER-3 (also known as ErbB-3) is a human epidermal growth factor receptor tyrosine kinases family member, and its expression in CRC (colorectal cancer) tissues was previously associated with poor prognosis." (PMID 37898642, 2023). "We detect the receptor tyrosine kinase activity in gefitinib-resistant colorectal cancer cells, ErbB3/EGFR is significantly activated and provides a potential multi-ErbB treatment target." (PMID 35319011, 2022). "Nrdp1 was shown to inhibit ErbB3 phosphorylation in colorectal cancer cells and suppress EGFR-MMP7 signaling-mediated metastasis." (PMID 35806132, 2022). "Using two mouse colorectal cancer models with variable the genetic backgrounds, we show that epithelial deletion of ERBB3 can result in outcomes ranging from inhibition to enhanced tumor growth." (PMID 34843459, 2021). "Taken together, this study raises substantial implications on the use of ERBB3 inhibitors against colorectal cancer." (PMID 34843459, 2021). "Overexpression of ERBB3 in poorly differentiated colorectal cancer cell lines led to a significant resistance to gefitinib in vitro and in vivo." (PMID 31703415, 2019). "We found significant elevation of ERBB3 mRNA levels in adenomas and colorectal cancers compared to normal tissues." (PMID 26367378, 2015). "Most interestingly, we determined that ERBB3 and several molecules which mark stem cell populations positively correlate at the RNA level in colorectal cancer." (PMID 26367378, 2015). "For instance, ERBB3 somatic mutations have been identified in 11% of colon cancers and several studies have shown that ERBB3 is expressed in 36–89% of colorectal cancers." (PMID 26367378, 2015). "Taken together, these data demonstrate that ERBB3+ colorectal cancer cells are predominantly non proliferative and differentiated, in contrast to EPHB2+ cells." (PMID 26367378, 2015).
colorectal cancer (continued). "The expression of ERBB3 was also investigated in 6 colorectal cancer cell lines by immunofluorescence." (PMID 26367378, 2015). "Following co-immunofluorescence and image analysis, the number of EPHB2+ and ERBB3+ cells was quantitated in 15 colorectal cancers (3500 cells per tumour)." (PMID 26367378, 2015). "Although the precise function of ERBB3 in colorectal cancer is not fully understood, several studies suggest that ERBB3 is disrupted in tumours." (PMID 26367378, 2015). "A qRT-PCR analysis of EPHB2 and ERBB3 expression levels was also conducted using 6 colorectal carcinoma cell lines." (PMID 26367378, 2015). "Taken together, our results show that colorectal cancer exhibits variation in oncogenic RTK due to different molecular patterns of expression including ErbB2/ErbB3/AKT and ErbB3/c-MET/MAPK." (PMID 24205104, 2013). "In the present study, we not only confirmed the over-expression of c-MET, ErbB2 and ErbB3 in human colorectal cancer, but also revealed the variation and complementary of these receptors." (PMID 24205104, 2013). "ErbB3 was significantly overexpressed in human colorectal cancer tissue, with expression mainly distributed in the membrane of cancer cells." (PMID 24205104, 2013). "By immunohistochemistry, we show here that RTK members ErbB2, ErbB3 and c-Met were in deed differentially overexpressed in colorectal cancer patient samples leading to constitutive activation of RTK signaling pathways." (PMID 24205104, 2013). "The partner of ErbB3 in the heterodimer, ErbB2, was also located mainly in the membrane of cancer cells and was similarly overexpressed in human colorectal cancer." (PMID 24205104, 2013). "Few studies have investigated the ErbB3 protein expression: the data obtained show that ErbB3 expression can be detected in 36-90% of colorectal cancer." (PMID 22889873, 2012). "ErbB3 level was correlated with worse prognosis of colorectal cancer patients." (PMID 34400880, 2021). "Based on the expression of EPHB2 stem cell marker and the ERBB3 differentiation marker, we tentatively propose that colorectal cancers are organised into i) stem-like cell enriched tumours, ii) differentiated tumours with a stem-like cell compartment or iii) lacking an EPHB2 stem cell compartment." (PMID 26367378, 2015). "Although these data are clearly indicative of an oncogenic potential for ERBB3, it is currently unknown whether ERBB3 regulates the colorectal cancer stem cell pool that is suggested to drive tumour initiation and tumour recurrence." (PMID 26367378, 2015). "Interestingly, cytokeratin 20 expression levels were down-regulated in colorectal cancer tissues compared to normal tissues, in contrast to ERBB3 in our studies, which suggests a more complex role for ERBB3." (PMID 26367378, 2015). "Our results show that ERBB3 and intestinal stem cell markers correlate in colorectal cancers." (PMID 26367378, 2015). "We analysed whether EPHB2, a defined stem cell marker, co-localised with ERBB3 expression in colorectal cancer tissues." (PMID 26367378, 2015). "In conclusion, our data suggest that EPHB2 and ERBB3 identify different sub-types of colorectal cancer, including stem cell enriched tumours (EPHB2+/ERBB3-), tumours that contain mutually exclusive compartments (EPHB2+/ERBB3+) or tumours lacking an EPHB2 stem cell compartment (EPHB2-)." (PMID 26367378, 2015). "Therefore, in the present study, we investigated the differential expression of RTKs c-MET, ErbB2, ErbB3, and down stream signaling molecules in primary samples of colorectal cancer patients, as well as in representative human colorectal cancer cell lines." (PMID 24205104, 2013). "While acquisition of novel mutations may be one of the possible explanations to this resistance in clinical treatment, activating mutations of several RTKs including ErbB2, ErbB3 and c-MET were discovered in human colorectal cancer and other cancers." (PMID 24205104, 2013).
colorectal cancer (continued). "Interestingly, a similar contrasting increase in fos and ErbB3 levels was found in normal colonic cells as compared to colorectal cancers in a SAGE study." (PMID 16001974, 2005). "In 68 patients with colorectal carcinoma (CRC), key driver mutations were detected as follows: KRAS, 40 (59%); NRAS, 1 (1%); BRAF, 4 (6%); ERBB2, 2 (3%); and ERBB3, 1 (1%)." (PMID 35323313, 2022). "Our results indicate that targeting ERBB3 in colorectal cancer using monoclonal antibodies, that are currently under development, may target differentiated cells and contribute to the elimination of the tumour bulk but may not affect the proliferative cancer stem-like cell population." (PMID 26367378, 2015). "Several studies have suggested ERBB3/HER3 may be a useful prognostic marker for colorectal cancer." (PMID 26367378, 2015). "In order to define whether ERBB3 signalling plays a role in the regulation of colorectal cancer stem cells, the expression of ERBB3 and intestinal stem cell markers were investigated in multiple colorectal tumours, including early stage adenomas and carcinomas (Stage I-IV)." (PMID 26367378, 2015). "Interestingly, most MUC2+ colorectal cancer cells were also EPHB2-/ERBB3+." (PMID 26367378, 2015). "Interestingly, ErbB3 was positive in all colorectal cancer tissues examined." (PMID 24205104, 2013). "For instance, the expression levels of both ErbB2 (HER2) and ErbB3 (HER3), the members of the RTK family, were found to be elevated in colorectal cancer (CRC) cells when exposed to Listeria monocytogenes supernatant." (PMID 39948481, 2025). "Analysis of expressed mutated surface genes revealed recurrent mutations in genes belonging to pathways known to be involved in colorectal cancer, including the WNT (LRP5 and FZD10), TGFβ (TGFBR3 and ACVR1B) and RTK-Ras (EGFR and ERBB3) signaling pathways." (PMID 25193853, 2014). "Consequently, L. monocytogenes promotes the proliferation and migration of colorectal cancer cells by upregulating the expression of RTK family members ErbB2 and ErbB3, and inducing the tyrosine phosphorylation of Met." (PMID 39948481, 2025). "In colorectal carcinoma, EGFR (ErbB1) signaling remains a cornerstone of oncogenic drive, while the HER2 (ErbB2) and HER3 (ErbB3) axis has gained increasing recognition for its role in tumor progression, therapy resistance, and compensatory signaling when EGFR is inhibited." (PMID 41515404, 2025). "There were no significantly discordant genes between primary colorectal cancer and CRLM; however, CDK12, ERBB3 and DICER1 were exclusively mutated in CRLM." (PMID 37057593, 2023). "More notably, the absence of ErbB3 expression in poorly differentiated colorectal cancer cells enhances gefitinib sensitivity." (PMID 35319011, 2022). "Indeed, it was also noticed that miR-22 targets Erb-B2 receptor tyrosine kinase 3 (ERBB3) and MDS1 and EVI1 complex locus (MECOM) in colorectal cancer." (PMID 33066509, 2020). "Our results show that most colorectal cancers we examined resemble normal tissue with distinct cell compartments and proliferative status and that a dual EPHB2/ERBB3 signature could identify tumours with this morphology." (PMID 26367378, 2015). "All the cases examined could be classified as: ErbB3: c-MET co-over-expression colorectal cancer, ErbB3:ErbB2 co-over-expression colorectal cancer, and ErbB3:ErbB2: c-MET co-over-expression colorectal cancer." (PMID 24205104, 2013). "In summary, our results show that elevated expression of ERBB3 and intestinal stem cell markers are common features of colorectal cancers and identify tumours that contain differentiated non-proliferative cell populations distinct from proliferative regions where cancer stem cells reside." (PMID 26367378, 2015).
colorectal cancer (continued). "In order to investigate further the mechanism of downstream signaling of both molecular patterns in colorectal cancer, cell lysates were utilized to analyze the activation of AKT and MAPK signaling which are well-known downstream signaling pathways of ErbB2/ErbB3 and ErbB3/c-MET complexes." (PMID 24205104, 2013). "In order to identify suitable human colorectal cancer cell lines corresponding to the three molecular patterns which we discovered in the human samples, the expression of ErbB2, ErbB3 and c-MET in 9 human colorectal cancer cell lines was analyzed by western blotting (data not shown)." (PMID 24205104, 2013).
prostate carcinoma (78 papers, 2005 to 2026). A carcinoma that arises from epithelial cells of the prostate gland. "A recent study revealed that the combined protein expression patterns of EGFR, ERBB2, and ERBB3 were associated with a higher risk of progression and mortality in prostate cancer." (PMID 36095024, 2022). "The linkage of EphA4 with prostate cancer associated receptor ERBB3/HER3 is apparent from the observed decrease of EphA4 transcript following the knockdown of ERBB3 in DU145 cells." (PMID 29682554, 2018). "A number of previous studies have already reported the association of EGFR, Her-2 and ErbB3 with PSA biochemical recurrence in prostate cancer patients." (PMID 20216540, 2010). "We and other groups have recently demonstrated an association between the nuclear localization of ErbB3, an epidermal growth factor receptor, and prostate cancer progression." (PMID 19025630, 2008). "It will be important to determine whether ERBB3-dependent signaling also contributes in a genetic background-dependent manner to tumorigenesis in other cancers such as breast, lung, and prostate cancers, where PI3K/AKT is also strongly implicated." (PMID 34843459, 2021). "In addition, overexpression of ErbB-2 and ErbB-3 has been implicated in the neoplastic transformation of prostate cancer." (PMID 22606295, 2012). "The FDA approved drugs vandetanib and bosutinib that bind to ERBB3 are in trials for the treatment of prostate cancer, suggesting their possible suitability for bladder cancer once approved." (PMID 35035776, 2022). "Arf6 expression is significantly elevated in prostate cancer clinical samples and it regulates ErbB3 nuclear localization in prostate cancer cells." (PMID 28830537, 2017). "The goal of this study was to bring out molecular pathways involving ErbB3 in tumour progression and metastatic spreading, in order to characterize new potential therapeutic targets for prostate cancer." (PMID 27191720, 2016). "Using the ErbB3 C-ter antibody, the nuclear staining we observed was restricted to PCa cells and was increased in advanced castration-resistant prostate cancer when compared to localized tumours." (PMID 27191720, 2016). "ErbB-related pathways were identified in the metastatic network, including the ErbB network pathway, ErbB4 pathway, Her2 pathway, ErbB2/ErbB3 signaling pathway and the EGFR pathway, which are implicated in prostate cancer progression and metastasis." (PMID 23782521, 2013). "The LNCaP androgen-dependent cell line expresses high levels of ErbB-2 and ErbB-3 compared to other human prostate cancer cells." (PMID 22606295, 2012). "Previous studies demonstrated that NRG (ErbB3 and ErbB4 ligand) inhibits growth of the androgen dependent LNCaP prostate cancer cells when cultured in complete medium while in the absence of androgen, NRG induced death of LNCaP cells." (PMID 22606295, 2012). "In summary, our multimarker analysis provides evidence that EGFR, Her-2 and ErbB3 are involved in the constitutive activation of Akt and NF-κB, which validates, for the first time in prostate cancer samples, previous in vitro data obtained in cell lines." (PMID 20216540, 2010). "A recent study in prostate cancer cell lines showed that an HER2/ERBB3 signalling pathway protected the AR from degradation by the ubiquitin–proteasome pathway and enhanced AR transcriptional activity at low androgen concentrations." (PMID 17211467, 2007). "Further studies are needed to characterise the interactions of ErbB3, Ebp1 and AR in the progression of prostate cancer." (PMID 15583694, 2005). "Besides, remedy with SC drastically brought about cell arrest at G0/G1 section and promoted cell apoptosis in prostate cancers typically by way of the circHMGCS1‐miR‐205‐5p‐ErBB3 signaling pathway." (PMID 37346933, 2023). "Studies have suggested a role for EGFR and ERBB3 in the development of prostate cancer (PC), while the involvement of ERBB2 and ERBB4 remains unclear." (PMID 33918389, 2021).